CD4 (CD4 molecule)
Diseases named in the same sentence as CD4 in open-access papers (continued):
Sharing a sentence is not in itself a finding about the gene and the disease.
T-cell lymphoma (166 papers, 2004 to 2025). "Transformation and proliferation of MD CD4+ T-cell lymphomas are associated with viral Meq and the induction of host factors such as COX-2 and TGF-β." (PMID 40733625, 2025). "The addition of immunophenotyping, as done in this case, further helps to differentiate CTCL from pseudo-T-cell lymphomas and cutaneous pseudolymphomas, which often lack the characteristic CD4+ predominance and CD7 loss seen in MF." (PMID 41523394, 2025). "This corroborates previous studies that found PTEN-mTOR pathway mutations in almost half of “Boxer type” canine T-cell lymphomas, which are most likely the CD4+ PTCL group being examined here." (PMID 38166662, 2024). "In enteropathy-associated T-cell lymphoma (types 1 and 2), primary cutaneous CD4 + small/medium T-cell lymphoma, peripheral T-cell lymphoma, NOS, and ALCL, ALK-negative, the error rates were 38.9, 75.0, 12.6, and 16.2%, respectively." (PMID 37046526, 2023). "Loss of CD5 expression has been reported in 43% of CD45+CD4+ T-cell lymphomas, whereas data concerning the expression of CD44 in different T-cell lymphoma subtypes are not available." (PMID 35448684, 2022). "Sézary syndrome (SS) is an aggressive variant of cutaneous t-cell lymphoma characterized by the accumulation of neoplastic CD4+ lymphocytes—the SS cells—mainly in blood, lymph nodes, and skin." (PMID 35740513, 2022). "In contrast, E2A deficieny was shown to lead to rapid development of T cell lymphomas expressing late markers CD4 and CD8." (PMID 34736527, 2021). "Marek’s disease virus (MDV), an alphaherpesvirus of poultry, causes Marek’s disease and is characterized by visceral CD4+TCRαβ+ T-cell lymphomas in susceptible hosts." (PMID 28475033, 2017). "MDV-associated CD4+ T cell lymphoma can only be developed in genetically susceptible chickens; however, the virus can replicate and be shed from both susceptible and resistant chicken lines." (PMID 27894330, 2016). "Several genome-wide transcription profiling studies have demonstrated high EPHA4 expression in Sézary syndrome (SS), a leukemic variant of cutaneous CD4+ T-cell lymphoma (CTCL) with an aggressive clinical course and poor prognosis." (PMID 26376612, 2015). "In this report, we describe a series of three cases of a rare subtype of primary small intestinal CD4+ T-cell lymphoma associated with a relatively indolent disease course." (PMID 23861889, 2013). "The positive expression of T-cell markers CD3 and CD4 may cause confusion with T-cell lymphoma in a scenario with undifferentiated morphology as in our case." (PMID 39776705, 2024). "MDV is an oncogenic virus causing CD4+ T cell lymphoma in chickens." (PMID 37631976, 2023). "In addition, CADM1 mediates cytotoxic lymphocyte recognition of tumor cells, including HTLV-1-associated CD4+ T cell lymphomas." (PMID 36270981, 2022). "Previous data from our laboratory showed that CD3 membrane expression was downmodulated after experimental infection of CD4+ T cells with HIV-1, HIV-2, as well as in patients with CD3- CD4+ T-cell lymphoma mediated hypereosinophilic syndrome, all linked to a specific defect in CD3γ gene transcripts." (PMID 17822534, 2007). "Currently, there are multiple ongoing phase I trials of CD4 CAR-T cells in T cell lymphoma (NCT04162340, NCT04712864, NCT03829540)." (PMID 41295262, 2025). "A minority of T-cell lymphomas are CD4+/CD45−, expressing high class II MHC and apparently show a more indolent disease course." (PMID 39943162, 2025). "Because the tumor cells were positive for LCA and CD4, T-cell lymphoma was considered in the differential diagnosis; however, the other T-cell markers, including CD3 and CD7, were negative." (PMID 41159020, 2025).
T-cell lymphoma (continued). "Two cases (50%) were reported with LyP (one of which was Type A), while the remaining cases were diagnosed with primary cutaneous small/medium CD4+ T-cell lymphoma (25%) and SS (25%)." (PMID 40226161, 2025). "The efficacy of the ITs was tested in both primary human T-cell blasts and C8166.R5 human CD4+ T-cell lymphoma cells." (PMID 41011175, 2025). "Other common types of CTCLs included SS (8/71, 11.2%), SPTCL (8/71, 11.2%), and primary cutaneous small/medium CD4+ T-cell lymphoma (5/71, 7%)." (PMID 40226161, 2025). "The strategy described offers a new therapeutic concept for patients suffering from CD4-driven T cell lymphomas." (PMID 39272178, 2024). "We present a case of vincristine-associated intestinal pseudo-obstruction in a 73-year-old male patient with stage III peripheral CD4+ T cell lymphoma." (PMID 39712677, 2024). "Both times, the FACS analysis clearly showed a host derived CD4+ T cell lymphoma and the few donor-derived cells present showed the appropriate normal percentages of CD3+, CD4+ and CD8+ cells, and presence of a significant proportion of CD45- erythroid cells." (PMID 38976688, 2024). "A 73-year-old male, diagnosed with stage III peripheral CD4+ T cell lymphoma, presented to the emergency care department with persistent abdominal discomfort and distention over the preceding 5 days." (PMID 39712677, 2024). "PC-SMTLD used to be called primary cutaneous CD4+ T-cell lymphoma at the WHO (2008) European Organization for Research and Treatment of Cancer." (PMID 37657958, 2024). "He had previously been diagnosed with stage III peripheral CD4+ T cell lymphoma and had initiated chemotherapy comprising vincristine two weeks prior to presentation." (PMID 39712677, 2024). "The Japanese reports described these children with chronic IM symptoms and EBV infected CD4 lymphocytes as progressing to a deadly EBV-positive T-cell lymphoma." (PMID 37803436, 2023). "The phenotype of indolent T-cell lymphoma of the gastrointestinal tract is either CD4+, CD4+/CD8+, or CD4−/CD8−, with CD4+ cases sometimes displaying STAT3::JAK2 fusions." (PMID 37762472, 2023). "T cell non-Hodgkin lymphomas (T-NHLs) represent a heterogeneous group of highly aggressive cancers that typically originate from mature CD4+ T cells." (PMID 37723306, 2023). "Mycosis fungoides is the most common primary cutaneous T-cell lymphoma, characterized by skin-homing CD4+ T cells derivation, indolent course, and low-grade of malignancy." (PMID 36833148, 2023). "CD4 was one of the first targets investigated for therapeutic purposes since it is expressed by a wide range of mature T-cell lymphomas and a subset of T-ALLs." (PMID 36624522, 2023). "The clinical manifestation of MD is associated with transient paralysis, immunosuppression, metabolic dysregulation, and CD4+ T cell lymphoma formation in infected chickens." (PMID 37631976, 2023). "In this study, NSG mice were inoculated with ex vivo HTLV-1-infected CD34+ hematopoietic progenitor and stem cells (HP/HSCs) and subsequently developed CD4+ T-cell lymphomas with elevated T-cell proliferation." (PMID 35602078, 2022). "The term “primary small/medium CD4+ T-cell lymphoma” was changed to “primary small/medium cutaneous CD4+ lymphoproliferative disorder” due to its indolent clinical behavior and uncertain malignant potential." (PMID 36363575, 2022). "Anti-CD4 CAR-T cells are potential targets showing promising results against T-cell lymphoma (CD4 positive) models in vivo and in vitro." (PMID 35814023, 2022). "The term “primary cutaneous small/medium CD4+ T-cell lymphoma” was changed to “primary cutaneous small/medium CD4+ lymphoproliferative disorder” due to its indolent clinical behavior and uncertain malignant potential." (PMID 36363575, 2022).
T-cell lymphoma (continued). "Background and objectives: Mycosis fungoides (MF) is the most common type of cutaneous T-cell lymphomas, characterized by mature, skin-tropic CD4+ T-helper cells." (PMID 36428999, 2022). "Hbz Tg mice developed T-cell lymphomas and system inflammation along with elevated levels of CD4+ Foxp3+ T(reg) cells and effector/memory CD4+ T cells." (PMID 35169839, 2022). "The late reactivation and immunosuppressive phases are also initiated in CD4+ T cells at approximately 18 dpi, and the final transformation phase is characterized by multiple organ tumors originating from CD4+ T cell lymphoma at approximately 28 dpi." (PMID 36680047, 2022). "HTLV-1 is the causative infectious agent of both an aggressive and fatal non-Hodgkin’s CD4+ T-cell lymphoma called ATL and a chronic, progressive neurodegenerative disease termed HAM/TSP." (PMID 35602078, 2022). "After four rounds of administration in mouse models, CD4 CAR-T cells suppressed the proliferation of T cell lymphomas and prolonged mice survival, compared to the control group." (PMID 36059451, 2022). "In vitro assessments demonstrated that these CAR-NKs exclusively eradicated various types of CD4-proficient patient-derived cell samples and cell lines of T-cell lymphoma and leukemia (including CCRF-CEM, KARPAS-299, and HL60) in a dose-dependent fashion." (PMID 34620233, 2021). "In our mouse model all mice invariably developed CD4+ T-cell lymphomas despite constitutive expression of the fusion protein in all hematopoietic lineages." (PMID 34140493, 2021). "Due to their morphologic, immunophenotypic, and clinical features, iTLPD-GIs have been postulated to be part of the spectrum of primary cutaneous CD4+ small/medium sized pleomorphic T-cell lymphomas, which are thought to be of TFH cell origin." (PMID 34205136, 2021). "Deletion of SOCS1, a negative regulator of the JAK family proteins, which was seen in a colonic CD4+ iTLPD, is a recurrent abnormality in a variety of T-cell lymphomas and more commonly reported in mycosis fungoides." (PMID 34205136, 2021). "For more than two decades, CD4-specific mAbs have been investigated in clinical trials for the treatment of T-cell lymphomas." (PMID 34620233, 2021). "After 3 months 100% of mice developed a T cell lymphoma/leukemia with rearranged TCRβ and either CD4 or CD8 surface expression." (PMID 34736527, 2021). "TCRβ clonality was confirmed in the CD4+PD1+CXCR5+ T cells for different plck-GAPDH tumors confirming a true T cell lymphoma." (PMID 32796826, 2020). "To test this, we took advantage of the CD4-positive human Jurkat T-cell lymphoma line in which we deleted the endogenous FCHO1 gene using CRISPR/Cas9 gene editing." (PMID 32098969, 2020). "It is possible that STAT3-JAK2 fusion gene promotes transition to aggressive T cell lymphoma as one of 5 CD4+ GI T-LPD case with the fusion protein was reported to develop T-cell lymphoma." (PMID 32850389, 2020). "As a consequence, the mice developed a CD4+ T-cell lymphoma displaying the typical Tcrα/δ-c-Myc chromosomal translocation." (PMID 31064074, 2019). "For instance, T-cell–selective deletion of Pten leads to a premalignant state in the CD4+CD8+ double-positive thymocyte population that is followed by development of CD4+ T-cell lymphomas in secondary lymphoid organs, including the lymph nodes and the spleen." (PMID 31064074, 2019). "Chicken CD4+ T-cell lymphoma induced by MDV is a key contributor to multiple visceral tumors and immunosuppression of chickens with Marek’s disease (MD)." (PMID 31035338, 2019). "Nevertheless, T-cell lymphomas were also observed when Pten was ablated at later stages of thymocyte development, by using the CD4-Cre system." (PMID 31064074, 2019). "CD4-NPM-ALK mice with intact Tyk2 developed aggressive T-cell lymphomas from about 12 weeks post-partum." (PMID 30131584, 2019).
T-cell lymphoma (continued). "Jurkat cells (a human CD4+ T cell lymphoma line) have been shown to express most TLRs, and 2G5 cell line in particular has been previously checked for surface expression of TLR2 and TLR4." (PMID 30500820, 2018). "Restricted HBZ expression to CD4+ T cells resulted in systemic inflammation and development of T cell lymphoma in only 30% of mice after a long latency period." (PMID 29643841, 2018). "Herein, we report on, to the best of our knowledge, the first case in the English literature of primary cutaneous CD4-positive small/medium-sized pleomorphic T-cell lymphoma in a cardiac transplant recipient." (PMID 28924466, 2017). "Marek’s Disease (MD) is caused by a highly contagious alphaherpesvirus, Marek’s Disease Virus (MDV), leading to development of malignant CD4+ T cell lymphoma in domestic chickens." (PMID 29267390, 2017). "Since transgenic expression of HBZ in CD4+ T cells induced both T-cell lymphoma and systemic inflammation in mice, it is clear that HBZ protein is also critical for the development of HTLV-1-associated diseases." (PMID 27117327, 2016). "Herein, we investigated gene expression data of five different mature T-cell lymphoma subtypes (n = 187) and found 21 genes to be up- and down-regulated across all malignancies in comparison to healthy CD4+ and CD8+ T-cell controls (n = 52)." (PMID 26566034, 2015). "Publically available, chip-matched GEO DataSets of mature T-cell lymphomas and healthy CD4+ and CD8+ T cells utilized for gene expression profiling." (PMID 26566034, 2015). "Genes significantly up- or down-regulated across all mature T-cell lymphoma subtypes as compared with healthy CD4+ and CD8+ T-cell controls." (PMID 26566034, 2015). "The T cell-specific deletion of PTEN results in elevated levels of B cells and CD4+ T cells in the periphery and increases thymic cellularity, resulting in CD4+ T cell lymphomas." (PMID 25295225, 2014). "As a model of ADCC, we cultured mouse NK cells together with a human CD4+ T cell lymphoma line (CCRF-CEM) in the presence of mouse anti-human CD4 monoclonal antibody." (PMID 24915189, 2014). "A 36-year-old woman was diagnosed with a therapy-refractory cutaneous CD4+ T-cell lymphoma, T3N0M0B0, and stage IIB." (PMID 24175298, 2013). "Unique pathobiologic features warrant designation of indolent small intestinal CD4+ T-cell lymphoma as a distinct entity, greater awareness of which would avoid misdiagnosis as EATL or an inflammatory disorder, especially celiac disease." (PMID 23861889, 2013). "We describe morphologic, phenotypic, genomic and clinical features of 3 cases of indolent primary small intestinal CD4+ T-cell lymphomas." (PMID 23861889, 2013). "In summary, we report a series of unique primary small intestinal CD4+ T-cell lymphomas exhibiting an indolent clinical course that are frequently misdiagnosed as celiac disease." (PMID 23861889, 2013). "Here, we present what is, to the best of our knowledge, the first report of a childhood case of appendiceal CD4-positive T-cell NHL and discuss the influence of H. pylori infection." (PMID 23302373, 2013). "We identified 3 cases of primary small intestinal CD4+ T-cell lymphomas, which occurred in 2 males and 1 female (ages 37, 50 and 53), all of western European descent." (PMID 23861889, 2013). "The relationship of the described indolent small intestinal CD4+ T-cell lymphomas with other rare types of indolent GI lymphoproliferative disorders (LPD) published in the English literature is unclear." (PMID 23861889, 2013). "T-cell lymphomas were similar both in phenotype (CD4+ or CD4+/CD8+) and latency (7–10 weeks) to those of VavP-MYC17 mice." (PMID 22393362, 2012).
T-cell lymphoma (continued). "KIR3DL2 expression is up-regulated on activated CD4 T cells and NK cells in SpA and circulating and T cell lymphoma cells in SS." (PMID 23162554, 2012). "HTLV-1-HU-NOD/SCID mice exclusively developed CD4+ T-cell lymphomas with characteristics similar to ATL." (PMID 23049525, 2012). "The recapitulation of a CD4+ T-cell lymphoma in HU-NOD/SCID mice suggests that HSCs provide a viral reservoir in vivo and act as cellular targets for cell transformation in humans." (PMID 23049525, 2012). "A more recent study shows that Tax-transduced human hematopoietic stem cells, a preferential HTLV-1 reservoir in vivo, acquire the ability to develop CD4+ T-cell lymphomas in SCID mice." (PMID 21743832, 2011). "Less than half of these infected mice developed T-cell lymphomas with a CD4+CD25low or CD4+CD25low phenotype." (PMID 21909275, 2011). "Here, we describe a monoclonal CD8+ CD4− αβ T cell receptor Vβ2+ CD28+ T cell lymphoma line, termed T8-28." (PMID 22163033, 2011). "It should be pointed out that the hbz gene induces T-cell lymphoma in mice when it is conditionally expressed in CD4+ T cells." (PMID 21743832, 2011). "In this study, we show that transgenic expression of HBZ in CD4+ T cells induced T-cell lymphomas and systemic inflammation in mice, resembling diseases observed in HTLV-1 infected individuals." (PMID 21347344, 2011). "Recent data from our laboratory demonstrates that ex vivo infection of CD34+ HP/HSCs with HTLV-1 reproducibly and consistently results in development of a CD4+ T-cell lymphoma in HU-SCID mice." (PMID 20132553, 2010). "Marek's disease (MD), a naturally occurring CD4+ T-cell lymphoma in chickens induced by Marek's disease virus (MDV), is considered to be a very good model for herpesvirus-induced rapid-onset T-cell lymphomas." (PMID 20441582, 2010). "As an example, a CD4-rich T-cell lymphomas was found to have developed in a R26-Ptenfx/fx mouse at six weeks post-treatment." (PMID 18043744, 2007). "Monoclonality was difficult to prove in T-NHL on FCI, however aberrant expression of T cell markers and predominant expression of CD4 or CD8 indicated T cell NHL." (PMID 17069647, 2006). "These include aggressive epidermotropic CD8+ CTCL, cutaneous γ/δ T-cell lymphoma (including cases formerly diagnosed as SPLTCL with a γ/δ phenotype) and primary cutaneous small–medium CD4+ T-cell lymphoma." (PMID 16623775, 2006). "Finally, a proliferative phase around 3 weeks is characterized by the formation of tumors that originate from CD4+ T-cell lymphomas." (PMID 40733625, 2025). "Most mature T-cell lymphomas in our cohort were CD4-positive and were characterised by abnormal immunophenotypic features, including an altered expression of antigens of the T-cell lineage (e.g., CD2, CD3, CD5, and CD7), and abnormal expression of additional antigens such as CD279 and CD10." (PMID 39796028, 2024). "In addition to MF, HEARTS is also delivered to patients with other diagnoses, such as therapy-refractory cutaneous CD4+ T-cell lymphoma, refractory acute myelogenous leukemia with extensive cutaneous involvement, and primary cutaneous T-cell lymphoma." (PMID 36901922, 2023). "If T-cell abnormalities are detected by flow cytometry, such as loss of pan T-cell antigens or a skewed CD4:CD8 ratio, these may suggest a T-cell lymphoma." (PMID 36814281, 2023). "The CD4-/CD8-phenotype has been in various anatomical forms of T-cell lymphoma." (PMID 37908841, 2023). "To further confirm the binding specificity of the tribodies for LAG-3, we investigated their binding and biological effects on the HuT78 cell line, which is derived from CD4+ human T cell lymphoma and expresses high levels of LAG-3 receptor, but low or absent levels of PD-1 and PD-L1." (PMID 35408827, 2022).